RAF1 (Raf-1 proto-oncogene, serine/threonine kinase)
Diseases named in the same sentence as RAF1 in open-access papers (continued):
Sharing a sentence is not in itself a finding about the gene and the disease.
Coats disease (1 paper, 2018). Coats disease (CD) is an idiopathic disorder characterized by retinal telangiectasia with deposition of intraretinal or subretinal exudates, potentially leading to retinal detachment and unilateral blindness. "In the group with NS due to a RAF1 mutation, we found 1 patient with a unilateral exudative retinopathy (Coats disease)." (PMID 29948256, 2018).
congestive heart failure (1 paper, 2021). Failure of the heart to pump a sufficient amount of blood to meet the needs of the body tissues, resulting in tissue congestion and edema. "A preterm infant with HCM carrying the RAF1:p.Ser257Leu variant, rapidly developed severe congestive heart failure (CHF) unresponsive to standard treatments." (PMID 35052347, 2021).
craniosynostosis (1 paper, 2024). Craniosynostosis is defined as the premature fusion of one or more cranial sutures leading to secondary distortion of skull shape resulting in skull deformities with a variable presentation. "Craniosynostosis has been described in individuals with pathogenic variants in other genes of the RAS/MAPK pathway including BRAF, KRAS, PPP1CB, SHOC2, PTPN11, RAF1, and HRAS." (PMID 37774117, 2024).
cyst (1 paper, 2012). A sac-like closed membranous structure that may be empty or contain fluid or amorphous material. "CXB can inhibit proliferation, suppress cell cycle progression, and induce apoptosis in ADPKD cyst-lining epithelial cells through the inhibition of the VEGF/VEGFR-2/Raf-1/MAPK/ERK signaling pathway." (PMID 22415852, 2012). "We found that VEGF secreted by cultured ADPKD cyst-lining epithelial cells bound to VEGFR-2 and directly activated the Ras/Raf-1/MAPK pathway to induce abnormal proliferation." (PMID 22415852, 2012).
de Barsy syndrome (1 paper, 2023). "Like for other progeroid conditions such as PYCR1 inactivation in De Barsy syndrome, this RAF1 loss‐of‐function phenotype provides another illustration of how genes that are hijacked in the context of cancer may inversely cause premature aging when inactivated." (PMID 37066513, 2023).
dermatitis (1 paper, 2020). An inflammatory process affecting the skin. "Recently, mice with epidermis-specific BRAF/RAF1 deficient also showed AD-like dermatitis, which is characterized by increased serum IgE levels and a Th2 response." (PMID 32792500, 2020).
ependymoma (1 paper, 2022). A WHO grade II, slow growing tumor of children and young adults, usually located intraventricularly. "Pathologists reported two cases (KANK1:NTRK2 and RAF1:QKI) as ependymomas, but these tumors were reclassified as low-grade glioma due to the clinical course, underlying molecular alteration, and methylation profile." (PMID 36163281, 2022).
epilepsy (1 paper, 2025). A brain disorder characterized by episodes of abnormally increased neuronal discharge resulting in transient episodes of sensory or motor neurological dysfunction, or psychic dysfunction. "We found that CDC25B, DNMT1, GZMA, MTX1, and SSH2 expression decreases epilepsy risk, whereas FGD3, RAF1, and SH3BP5L increase it." (PMID 39753851, 2025).
Ewing sarcoma (1 paper, 2020). A small round cell tumor that lacks morphologic, immunohistochemical, and electron microscopic evidence of neuroectodermal differentiation. "Moreover, in the same study, in Ewing sarcoma, exposure to PU-H71 resulted in depletion of critical proteins, including AKT, pERK, Raf-1, c-MYC, c-KIT, IGF1R, hTERT, and EWS-FLI78." (PMID 32895397, 2020).
glioneuronal tumor (1 paper, 2023). "More recently, a novel MC of glioneuronal tumor (called the “glioneuronal tumor, not otherwise specified, subtype A") harboring RTK (ALK, NTRK1, NTRK2, NTRK3, and MET) fusions and MAPK (RAF1) fusions have been isolated by DNA‐methylation profiling." (PMID 37349135, 2023).
HIV-1 infection (1 paper, 2014). The type species of lentivirus and the etiologic agent of acquired immunodeficiency syndrome (AIDS). "It has been demonstrated that RAF-1 plays a role in HIV-1 infection in dendritic cells, and that it is required for the induction of proviral transcription." (PMID 25295610, 2014).
hyperlipidemia (1 paper, 2025). "Therefore, the current study suggests that genes involved in these directly related hyperlipidemia pathways such as RAF1, GRK3 and CXCR2 were significant feature genes associated with hyperlipidemia." (PMID 41446394, 2025). "The hub genes such as RAF1, GRK3 and CXCR2, might be potential genetic biomarkers of hyperlipidemia." (PMID 41446394, 2025). "At the same time, the feature genes, including RAF1, GRK3 and CXCR2 may be potential genetic biomarkers of hyperlipidemia." (PMID 41446394, 2025).
hypothyroidism (1 paper, 2020). Abnormally low levels of thyroid hormone. "At a gene level, PTPN11, NRAS, RASA2, SOS2, MAP2K1, and RAF1 were significantly associated with hypothyroidism, diastolic and systolic BP, birth weight, growth abnormality, subcutaneous adipose tissue, standing/sitting height ratio and body mass index." (PMID 33226994, 2020).
left ventricular noncompaction (1 paper, 2025). Left ventricular noncompaction (LVNC) is a rare cardiomyopathy characterized anatomically by prominent left ventricular trabeculae and deep intratrabecular recesses causing progressive systolic and diastolic dysfunction, conduction abnormalities, and occasionally thromboembolic events. "These include MYBPC3 mutations in HCM, TBX20 (OMIM: 606061) mutations in left ventricular noncompaction (LVNC), and RAF1 (OMIM: 164760) mutations implicated in HCM associated with Noonan syndrome." (PMID 40507801, 2025).
lung diseases (1 paper, 2020). "Further extention of this study to in vivo models will advance our understanding of mucin/mucus regulation by A. fumigatus and further establish a Protease/Ras/Raf1/ERK axis as a novel therapeutic target for treating lung diseases caused by environmental mold exposure." (PMID 32320453, 2020).
Lymphatic Metastasis (1 paper, 2022). Transfer of a neoplasm from its primary site to lymph nodes or to distant parts of the body by way of the lymphatic system. "It suggested that the positive expression rate of p-RAF1 was significantly higher in the group with lymphatic metastasis (66/82, 80.5%) than in the group without lymphatic metastasis (9/31, 29.0%)." (PMID 35668458, 2022).
malignant pleural mesothelioma (1 paper, 2025). A malignant neoplasm that arises from mesothelial cells in the pleura and shows a diffuse growth pattern. "A study on malignant pleural mesothelioma demonstrated that ADM induces cell proliferation in vitro through the activation of the Raf1 proto-oncogene serine/threonine kinase (c-Raf)/mitogen-activated protein kinase 1 (MEK)/ERK pathway." (PMID 40565016, 2025).
medullary thyroid cancer (1 paper, 2021). "The Raf-1 signal was activated by XH, which led to inhibition of ASCL1, an important factor in medullary thyroid cancer development." (PMID 33923053, 2021).
medulloblastoma (1 paper, 2016). A malignant, invasive embryonal neoplasm arising from the cerebellum. "An intriguing observation concerns the fact that three genes in Set A whose expression is significantly modified - namely, Nlk, Raf1, and Ppp2r2b—are markers for group 3 medulloblastoma." (PMID 27965576, 2016).
melanocytic neoplasm (1 paper, 2020). "Reports of activating RAF1 fusions in melanocytic neoplasms have been rare." (PMID 32123303, 2020).
memory impairment (1 paper, 2024). "Similarly, the RAF inhibitor sorafenib reversed memory impairment and decreased the expression of APP, Cox-2, and iNOS in the brain of an AD transgenic mouse model, highlighting the potential of targeting RAF1." (PMID 39000011, 2024).
Myocardial fibrosis (1 paper, 2025). "NOX2 facilitates ROS production and activates the Raf‐1/extracellular signal‐regulated kinases 1/2 (ERK1/2) signaling pathway to mediate myocardial fibrosis." (PMID 40548179, 2025). "In addition, the molecular mechanism of naringin in myocardial fibrosis is mediated by the AT1R/PKC/NOX2/Raf‐1/ERK1/2 signaling pathway." (PMID 40548179, 2025).
neuropathy (1 paper, 2022). A disorder affecting the nervous system that manifests with pain, tingling, numbness, and/or muscle weakness. "Dead M. leprae increased the expression of WNK, IFNB, IKBKA, and HLA-DQA1 (genes related to neuropathy), in addition to GJA1 and RAF1 (for Schwann cell reprogramming) and KCNJ10, OLIG1, SHH, and SOSTDC1 (for neural regeneration)." (PMID 35492305, 2022).
neutropenia (1 paper, 2020). A decrease in the number of neutrophils found in the blood. "In this region, several candidate genes (GATA2, PPARG, RAF1 and SEC61A1) associated with functions such as quantity of leukocytes or neutropenia were identified." (PMID 33116177, 2020).
osteoporosis (1 paper, 2024). A condition of reduced bone mass, with decreased cortical thickness and a decrease in the number and size of the trabeculae of cancellous bone (but normal chemical composition), resulting in increased fracture incidence. "Our data indicated that activation of the Ras/Raf1/Mek/Erk signaling pathway plays a critical role in the regulation of proliferation and osteogenic differentiation of BMSCs in vitro and ameliorate osteoporosis in vivo." (PMID 38948067, 2024). "Taken together, these results support our conclusion that ApoEVs from apoptotic BMSCs post-transplantation facilitate bone formation in osteoporosis mice via the Ras/Raf1/Mek/Erk pathway." (PMID 38948067, 2024).
pheochromocytoma (1 paper, 2023). "Furthermore, an additional experiment provided data according to which constitutively active Ras and Raf-1 (C-Raf) led to an increase in basal CgA activity in PC12 (rat pheochromocytoma) cells." (PMID 36902417, 2023).
prostate (1 paper, 2016). "Our data provide direct evidence implicating that ARF1-mediated Raf1/MEK/ERK1/2 signaling is critical for prostate tumorigenesis and that genetic approaches targeting ARF1 in animal models may provide an important and novel avenue for studying tumorigenesis and developing therapeutics." (PMID 27213581, 2016).
pulmonary hypertension (1 paper, 2021). Increased pressure within the pulmonary circulation due to lung or heart disorder. "In a newborn affected by a severe phenotype of NS with progressive HCM and pulmonary hypertension, due to a RAF1 p.Ser257Leu variant, we reasoned that MEK inhibition might limit the progression of cardiac disease." (PMID 35052347, 2021). "Indeed, the p.Ser257Leu variant in RAF1 has been causally associated with severe pulmonary arterial hypertension and progressive HCM with lethal outcome." (PMID 35052347, 2021). "Here, we report on a RAF1-mutated patient with severe NS, including neonatal HCM and pulmonary hypertension, treated with selective MEK inhibition by Trametinib." (PMID 35052347, 2021). "Notably, the RAF1(NM_002880):c.770C>T (p.Ser257Leu) variant is associated with a severe clinical phenotype of NS with neonatal HCM and pulmonary hypertension." (PMID 35052347, 2021).
retinal degeneration (1 paper, 2023). Degeneration of the retina. "The combined data thus clearly indicate the participation of RAF1 activities in retinal degeneration during the 2 h of PKG inhibition, albeit in an unclarified mechanism." (PMID 37372984, 2023). "Therefore, as part of the well-established Ras/Raf-1/MAPK1 signaling, the role of RAF1 during retinal degeneration and its connection with the cGMP-PKG system was of interest to analyze further." (PMID 37372984, 2023). "This showed that the RAS/RAF1/MAPK/ERK pathway may be involved in retinal degeneration in a yet unclarified mechanism, thus deserving further investigation in the future." (PMID 37372984, 2023). "It appears likely that several of these results, including those connected to the RAS/RAF1/MAPK/ERK pathway, relate to the yet unclarified mechanisms of inherited retinal degeneration and, as such, will aid in designing future investigations in this area." (PMID 37372984, 2023). "Given that retinal degeneration benefits from such PKG inhibition, RAF1 may exert neuroprotective effects during photoreceptor death." (PMID 37372984, 2023).
Sepsis (1 paper, 2021). Sepsis is defined as life-threatening organ dysfunction caused by a dysregulated host response to infection. "Previous studies demonstrated that a specific inhibition of AGER, MAPK1, MAPK3, and RAF1 signaling reduced the expression of inflammatory cytokines and had beneficial effects during lethal sepsis." (PMID 34948374, 2021).
solitary fibrous tumor (1 paper, 2022). Solitary fibrous tumor (SFT) represents a diverse group of ubiquitous rare spindle cell neoplasms that may be benign or malignant and that most frequently arises from the pleura and peritoneum and rarely from other sites such as head and neck, liver and skeletal muscle. "In AF0062, the first RAF1 fusion-positive case, a 49-year-old woman was referred to the hospital for a recurrent tumor in the left sacrum, which was diagnosed as a solitary fibrous tumor at a different hospital." (PMID 36033527, 2022).
undifferentiated pleomorphic sarcoma (1 paper, 2022). An undifferentiated soft tissue sarcoma characterized by the presence of a pleomorphic malignant cellular infiltrate. "We discovered novel RAF1 fusions in two cases of malignant peripheral nerve sheath tumor and undifferentiated pleomorphic sarcoma." (PMID 36033527, 2022).
yang deficiency (1 paper, 2022). Yang deficiency is a concept from traditional Chinese medicine. "The symptomatic gene targets for Yang deficiency (KAT2B, NFKB2, CREBBP, GTF2H3) or Yin deficiency (JUNB, JUND, NGLY1, TNF, RAF1, PPP1R15A) were potentially discovered." (PMID 35341155, 2022).
tumor (402 papers, 2002 to 2026). "In linear regression models, we identified Raf1‐associated gene pairs in primary tumours relative to cell pools including Raf1‐Pkm2, Raf1‐Top2α, Raf1‐Nqo1, Raf1‐Alox5, Raf1‐Chrnb1 and Raf1‐ Rxra in the model (outlier test, adjusted p < .05)." (PMID 39073026, 2024). "Activating mutations of Ras GTPases, which are the upstream activators of RAF1, occur in about 19% of human neoplasms, and BRAF is mutated in about 7% of all cancers." (PMID 35203304, 2022). "Of interest, RAF1 downregulation in a conditional mouse model for RAF1-induced lung tumorigenesis led to tumor regression associated with an enhanced autophagic flux." (PMID 34685497, 2021). "RAF1 was previously implicated in the carcinogenic process in human cancers and associated with tumor angiogenesis." (PMID 34572445, 2021). "In agreement with our previous studies, only vMCF-7∆Raf1 tumor xenografts developed spontaneous lung metastases, corroborating the causal role of aberrant activation of Raf-1/MAPK pathway in promoting metastatic lesions." (PMID 30180881, 2018). "RASSF1, a member of the Ras association domain family, is known as a tumour suppressor that inhibits RAF1 signalling and activates MST131." (PMID 28205554, 2017). "Taken together, the results show that the molecular defects observed in RAF1-deficient tumour-bearing livers and in human HCC lines were already present in P-HEPS and did not arise during transformation or immortalization." (PMID 28000790, 2016). "In Δp/np animals, the failure of RAF1-deficient macrophages to migrate in response to chemokines and infiltrate the tumour-bearing livers correlates with limited inflammation and tumour load." (PMID 28000790, 2016). "Consistent with the slightly elevated CCL2 levels in tumour-bearing Δp/np mice, RAF1-deficient hepatocytes expressed higher basal and LPS-induced levels of this chemokine." (PMID 28000790, 2016). "The competitive advantage of RAF1-deficient initiated hepatocytes is still evident in the Δp/np animals in the form of increased tumour multiplicity." (PMID 28000790, 2016). "The expression of βcatenin, frequently activated in HCC, was slightly elevated in tumours of both genotypes; in addition, its subcellular localization was similar in RAF1 deficient and proficient tumours." (PMID 28000790, 2016). "This paradoxical activation of ERK occurs in tumor cells with Ras mutations, which cooperate with Raf inhibitors to induce B-Raf-Raf-1 heterodimerization." (PMID 22035226, 2011). "Moreover, there was a negative association between miR-431-5p expression and FBXL19-AS1 or RAF1 expression in tumor tissues." (PMID 30610161, 2019). "Regarding pathway assignments of at least 20 HRO tumours, 10 top-ranked genes, of which 9 were lost in 3p, were linked with 7 to 45 pathways (n = 280) comprising RAF1 (45 PWs), RHOA (25 PWs), IPTR1 (22 PWs), CACNA1D, ITGA9 (8PWs), WNT7A (8 PWs) TLR9 (7PWS9, LAMB2 (7 PWs) and ARPC4 (6 PWs)." (PMID 28486536, 2017). "Raf1 has also been implicated in organ regeneration, therefore may induce angiogenesis, which is essential for tumor growth." (PMID 28978120, 2017). "The tumor growth inhibition was associated with a reduction in tumor Raf-1 protein levels." (PMID 21044336, 2010). "In addition, Raf-1 is an effector of the protein product of the ras oncogene, which is often found to be mutated in malignantly transformed cells; this is why therapy directed at suppressing raf-1 can prove to be effective against ras-mediated neoplasias." (PMID 22649602, 2009). "RAF1 is essential for KRAS-driven tumor maintenance through kinase-independent survival functions, making it an attractive candidate for targeted protein degradation." (PMID 41650121, 2026). "Despite being consistently acknowledged as an activator of tumorigenic pathways, limited insights into the tumor-suppressive functions of RAF1 have been documented." (PMID 40362553, 2025).